VDAC3P1 (voltage dependent anion channel 3 pseudogene 1)
Synonyms: formerly VDAC3P
Gene: Processed pseudogene on chromosome 14 (99,964,529 to 99,965,378, forward strand). Ensembl gene ENSG00000271198.
Diseases named in the same sentence as VDAC3P1 in open-access papers:
VDAC3P1 is named in the same sentence as 1 disease in open-access papers, as found by Europe PMC text mining. Sharing a sentence is not in itself a finding about the gene and the disease.
VDAC3P1 shares sentences with these, for which no sentence is quoted: sarcoma (1 paper).